Y_RNA (Y RNA )
Gene: Miscellaneous RNA gene on chromosome 2 (206,701,065 to 206,701,185, reverse strand). Ensembl gene ENSG00000207319.
Homologues: Orthologues: chimpanzee Y_RNA (90% identical), macaque Y_RNA (86% identical). Paralogues in human: RNY1P5 (79% identical), Y_RNA (78% identical), Y_RNA (77% identical), Y_RNA (76% identical), Y_RNA (75% identical), Y_RNA (74% identical), RNY1P1 (74% identical), Y_RNA (73% identical), Y_RNA (72% identical), RNY1P2 (71% identical), Y_RNA (71% identical), RNY1 (70% identical), and 91 more.